G6PD (glucose-6-phosphate dehydrogenase)
Diseases named in the same sentence as G6PD in open-access papers (continued):
Sharing a sentence is not in itself a finding about the gene and the disease.
tumor (continued). "Consistent with the database predictions, TTC1 and G6PD mRNA levels were markedly higher in tumor tissues than in matched normal tissues, which mirrors their elevated protein levels in tumors." (PMID 41268553, 2025). "Tumor cells induce H3K9me3 deposition at the promoter of G6PD, resulting in decreased G6PD and granzyme B expression in tumor-specific cytotoxic T cells." (PMID 39859324, 2025). "The results revealed that knocking down G6PD significantly inhibited the promoting effect of NAT10 overexpression on tumor growth in the nude mice." (PMID 40303290, 2025). "Taken together, the results of in vivo experiments further supported that BANCR OE inhibited G6PD activity through post-transcriptional regulatory mechanisms, thereby limiting the tumor growth of ccRCC cells." (PMID 39894218, 2025). "G6PD regulates granzyme B expression in tumor-specific cytotoxic T lymphocytes as a metabolic checkpoint." (PMID 38194707, 2024). "Moreover, despite the reduction in the de novo lipogenesis due to G6PD loss, the absorption of fatty acids from dietary sources in fed state might play an important role in maintaining the fatty acid levels in G6pdKO;KL tumors for tumor growth." (PMID 38997257, 2024). "As G6PD is the most critical enzyme in intracellular NADPH generation, the targeted inhibition of G6PD overexpression in tumor cells is an important strategy." (PMID 39061847, 2024). "Several studies suggested a correlation between high G6PD expression and prolonged survival of tumor cells, correlating with poor prognosis and insurgence of drug resistance." (PMID 38115544, 2024). "Pathway analysis of bulk-tumor mRNA-seq of KL lung tumors revealed that G6PD ablation significantly altered lipid metabolism by downregulating the pathways related to lipid and fatty acid biosynthesis." (PMID 38997257, 2024). "As shown by multivariate analysis, the G6PD (HR = 1.338, 95% CI = 1.177–1.521, p < 0.001) and Tumor stage (HR = 1.588, 95% CI = 1.279–1.970, p < 0.001) were considered as the critical prognostic factors that forecasted the OS for LIHC." (PMID 38297250, 2024). "Based on these data, it can be concluded that HCP5‐132aa primarily inhibits ferroptosis by regulating the expression of SLC7A11 and G6PD, thereby promoting malignant proliferation and tumor progression in GC." (PMID 39447131, 2024). "When we knocked down IGF2BP1, 2 and 3 in tumor cells via siRNA transfection, only siIGF2BP2 markedly decreased the G6PD mRNA and protein expression level through reducing mRNA stability." (PMID 39138186, 2024). "G6PD has potential oncogenic activity and is related to several cell biological processes in metabolism and redox of tumor progression." (PMID 38194707, 2024). "In summary, we demonstrated that G6PD maintains KL lung tumor redox homeostasis to prevent oxidative stress-induced cell death, which is critical for tumor growth." (PMID 38997257, 2024). "We measured the protein level of G6PD in the tumor tissues and lung organs from BALB/c nude mice by immunofluorescence, and hypoxia-induced PAH tissue and normal lung tissue from the (SD) rats and mice by immunofluorescence." (PMID 38194707, 2024). "The results indicated that G6PD had a higher level in tumor tissues than lung tissue and a higher level in hypoxia-induced PAH tissues than normal lung tissue." (PMID 38194707, 2024).
tumor (continued). "G6PD expression was completely deleted in KP and KL lung tumors, which was validated by immunohistology (IHC) and mRNA expression from KL bulk-tumor mRNA-seq." (PMID 38997257, 2024). "This study has identified the critical role of up-regulated METTL14 in enhancing gene expression of G6PD, thereby promoting tumor growth and metastasis in LUAD." (PMID 39138186, 2024). "Immunofluorescence results showed that G6PD had a higher protein level in tumor tissues than in normal lung tissue and a higher protein level in hypoxia-induced PAH tissues than in normal lung tissue." (PMID 38194707, 2024). "When the high expression of G6PD resumed, the tumor growth, tumor size, volume, and weight were restored." (PMID 38297250, 2024). "As tumors progress, G6PD-deficient KL tumors increase an alternative NADPH source from serine-driven one carbon metabolism, rendering associated tumor-derived cell lines sensitive to serine/glycine depletion." (PMID 38997257, 2024). "The G6PD inhibitor dehydroepiandrosterone (DHEA) has demonstrated anti-tumor activity by repressing DNA synthesis and inhibiting G6PD uncompetitively." (PMID 39796677, 2024). "In contrast, KP lung tumors can swiftly adapt to G6PD loss due to their functional LKB1-AMPK signaling, ensuring tumor survival." (PMID 38997257, 2024). "In the tumor microenvironment, enzymes like intracellular glucose-6-phosphate dehydrogenase (G6PD) are involved in various metabolic pathways, such as the pentose phosphate pathway (PPP)." (PMID 39136031, 2024). "First, we explored the relationship between G6PD and Age, Gender, Grade, Tumor stage and TNM stage, and found that G6PD expression level was dramatically different in Grade, Tumor stage and T stage, respectively." (PMID 38297250, 2024). "Research has shown that glucose-6-phosphate dehydrogenase (G6PD) serves as a metabolic checkpoint in tumor-activated cytotoxic T lymphocytes." (PMID 39609317, 2024). "G6PD was reported as a promoter in tumor growth, invasion, and metastasis, correlating with a poor prognosis." (PMID 38170006, 2023). "Pre-clinical studies have shown potential in using G6PD inhibitors to induce apoptosis in tumor cells." (PMID 38139067, 2023). "The crucial functional role of G6PD in influencing tumor cells mainly involves the production of NADPH and R5P, both of which are essential for maintaining redox homeostasis and for biomacromolecule synthesis." (PMID 38139067, 2023). "RMRP was found to be related to BLCA tumor progression and the cell migration and invasion processes via the miR-206/G6PD axis both in vitro and in vivo." (PMID 37958478, 2023). "Genes in the 34-gene signature included G6PD (glucose-6-phosphate dehydrogenase), which affects tumor development by regulating several metabolic pathways." (PMID 37704602, 2023). "Combined with previous studies, we believe that the regulation of G6PD on tumor cells and its impact on prognosis is multifaceted." (PMID 37601657, 2023). "In conclusion, research on the molecular mechanisms of the G6PD-mediated PPP is closely related to YY1-induced tumor cell proliferation and tumorigenesis." (PMID 37081988, 2023). "Specifically, we demonstrated that p52-ZER6 promotes tumor glucose metabolic reprogramming by positively regulating the transcription of glucose-6-phosphate dehydrogenase (G6PD), the rate-limiting enzyme in the pentose phosphate pathway (PPP)." (PMID 36977688, 2023). "Initially, to reveal G6PD expression specificity, we utilized the data from the TCGA database to analyze the differences in G6PD expression levels in tumor and adjacent normal tissues." (PMID 37601657, 2023). "G6PD upregulation in tumor cells enhances their anti-oxidant activity, helping in the maintenance of ROS balance, preventing cell cycle arrest, and enhancing proliferation." (PMID 38139067, 2023). "A heatmap between normal and tumor tissues showed the expression of G6PD, HRAS, NRAS, TIMM9, and MYCN." (PMID 37143953, 2023).
tumor (continued). "In vivo study also supported that downregulation of G6PD exacerbated tumor growth inhibition by Escin." (PMID 37149513, 2023). "This review provides an overview of the structural significance of G6PD, its role in and regulation of tumor development and progression, and the strategies explored in relation to G6PD-targeted therapy." (PMID 38139067, 2023). "In summary, our findings reveal a novel function of p52-ZER6 in inducing tumor cell metabolic reprogramming by directly promoting G6PD transcription." (PMID 36977688, 2023). "Collectively, these findings reveal a novel function of PBX3 as a regulator of G6PD, linking its oncogenic activity with tumor cell metabolic reprogramming, especially PPP." (PMID 37781025, 2023). "There was a positive correlation between G6PD expression levels and tumor stages, such as KIRP, BRCA, KIRC, and LIHC." (PMID 37601657, 2023). "Compared with the sh-NC group, both the Escin treatment group and the G6PD knockdown group showed slight inhibition of tumor growth." (PMID 37149513, 2023). "Nevertheless, our current finding is the first that shows a crucial role of PBX3 in regulating tumor cell metabolic reprogramming through its regulation of G6PD." (PMID 37781025, 2023). "Taken together, these results suggest that Escin inhibits tumor growth in vivo and in vitro via regulating the ferroptosis mediated by G6PD/GPX4 axis." (PMID 37149513, 2023). "Targeting G6PD with 6-AN can enhance the sensitivity of tumor cells to these drugs, suggesting the potential of combining G6PD inhibitors with conventional anti-tumor drugs." (PMID 38139067, 2023). "Next, to figure out the potential mechanism of G6PD’s roles in tumorigenesis and tumor progression of LIHC, we constructed a PPI network including 1566 edges and 60 nodes." (PMID 37601657, 2023). "The expression of both PBX3 and G6PD mRNA in tumor lesions increased significantly compared to adjacent tissues." (PMID 37781025, 2023). "There was a significant increase in G6PD expression in grade 4 compared to grade 2 ccRCC tumours, while all stages of tumours had significantly higher expression of G6PD than normal kidney tissues." (PMID 37174052, 2023). "In conclusion, we report an unprecedented link between p52-ZER6 and tumor cell metabolic reprogramming, which involves activation of the G6PD/PPP axis and subsequent tumorigenesis." (PMID 36977688, 2023). "The expression of CYP2A6 and CYP2C9 were relatively lower in tumor tissues, while the expression of G6PD in HCC tumors was higher in tumor tissues than in normal tissues." (PMID 37051536, 2023). "Despite these challenges, the development of potential drugs targeting G6PD with better clinical efficacy remains a promising avenue for anti-tumor therapy." (PMID 38139067, 2023). "Together, these results suggest that PBX3 is a positive regulator of G6PD and is crucial for glucose metabolic reprogramming in tumor cells." (PMID 37781025, 2023). "For instance, in non-tumor cells such as adipocytes, increased G6PD expression has been observed to stimulate oxidative stress and inflammatory responses." (PMID 38139067, 2023). "Although DHEA can induce apoptosis in tumor cells through G6PD inhibition, clinical trials of DHEA have been held back due to the high oral dose required and the difficulty in converting DHEA to active androgen." (PMID 38139067, 2023). "To date, anti-tumor drugs inhibiting G6PD or PPP have been widely applied or are undergoing clinical trials, such as Polydatin, Dehydroepiandrosterone (DHEA)." (PMID 37601657, 2023). "G6PD overexpression in tumor cells aids tumor cell proliferation, survival, and invasion, as well as drug resistance." (PMID 38139067, 2023).
tumor (continued). "As a key enzyme of PPP, G6PD plays a pivotal role in the development of tumor and the occurrence of drug resistance in various tumors." (PMID 38111012, 2023). "We found that the expression of G6PD in tumor tissues was significantly higher than that in the corresponding adjacent normal tissues, which was consistent with the results of the TCGA database." (PMID 37601657, 2023). "Meanwhile, inhibition of G6PD/PPP through G6PD knockdown results in decreased tumor cell proliferation." (PMID 38139067, 2023). "Adjoining normal kidney tissue showed diffused mild positive staining in the tubules, while ccRCC tumours showed uniform moderate cytoplasmic staining for G6PD." (PMID 37174052, 2023). "In the proteomic data of the CPTAC cohort, G6PD was also significantly highly expressed in HCC tumor tissues compared to normal tissues, while the remaining four proteins were significantly less expressed, consistent with the results of immunohistochemistry." (PMID 37051536, 2023). "In this study, we found that the expression of G6PD in tumor tissues was significantly higher than that in normal tissues, which was also confirmed by immunohistochemical analysis." (PMID 35938165, 2022). "We used R to determine the expression levels of G6PD in tumour and normal tissues, and based on the information obtained, we analysed the correlation between G6PD and the prognosis of patients with HCC as well as the biological role of G6PD." (PMID 35712981, 2022). "Pentose phosphate has an important function in the metabolic reprogramming of tumor cells and is usually mediated through glucose-6-phosphate dehydrogenase (G6PD)." (PMID 35801241, 2022). "Inhibition of Trx-1 and G6PD, together with inhibition of glycolysis using 2-deoxy-D-glucose (2DG), resulted in significant anti-tumor effects in CRC xenografts in vivo." (PMID 36147458, 2022). "In that context, the high oxidative burden in the tumor cells likely creates a dependency on the G6PD and TrxR1 functions as part of the adaptation mechanisms for tumor cell survival, given the roles of the two targets in cellular redox events." (PMID 36473850, 2022). "G6PD is therefore a potential molecular target for metabolic reprogramming of tumor-specific CTLs to improve immunotherapy." (PMID 36569893, 2022). "In tumors, G6PD levels increase with tumor grade and the enzyme is targeted by miR-206 and miR-1 in cervical cancers associated with papillomavirus infections, whereas it is downregulated by miR-1 in pituitary tumors." (PMID 35348905, 2022). "Meanwhile, G6PD glycosylation enhances PPP flow to the building blocks of macromolecular biosynthesis promoting the proliferation of tumor cells." (PMID 36091812, 2022). "In this review, we focus on current findings in post-translational modifications (PTM) of G6PD and their roles in tumorigenesis and pathogenesis of non-neoplastic diseases." (PMID 36091812, 2022). "G6PD expression was also correlated with eight types of immune cells in the tumour immune microenvironment and positively correlated with the expression of three types of immune checkpoints." (PMID 35712981, 2022). "The results indicated that G6PD changed cell cycle dynamics, facilitated cell proliferation, promoted migration in vitro, and enhanced ccRCC tumor growth in vivo, probably by upregulating Cyclin E1 and MMP9." (PMID 34975298, 2022). "Inhibition of Trx-1 and G6PD in combination with inhibition of glycolysis using 2-deoxy-D-glucose (2DG) resulted in a substantial anti-tumor effect in CRC xenografts in vivo." (PMID 36147458, 2022).
tumor (continued). "Evidence has shown that G6PD is essential for cell growth, survival and embryonic development through redox-sensitive mechanisms and is therefore upregulated in several tumor types." (PMID 35493106, 2022). "Our findings show that RIP140 negatively regulates G6PD activity, at least in transformed MEFs, thus strengthening its link with tumor cell metabolic reprogramming." (PMID 35806424, 2022). "PC3-EGFP G6PD knockdown cells or a scrambled control were injected via intratibial inoculation into the right leg of nude mice and longitudinal tumor growth was assessed by in vivo fluorescence imaging." (PMID 35213227, 2022). "Increased miR-1-3p can suppress G6PD, promote apoptosis, reduce tumor cell glycolysis, and inhibit cell proliferation." (PMID 36185280, 2022). "Accordingly, the tumor weight was significantly increased in the G6PD-OE group compared with the WT group." (PMID 36271440, 2022). "Numerous studies have revealed a significant upregulation of glucose-6-phosphate dehydrogenase (G6pd) in tumor cells." (PMID 36406265, 2022). "We found that the expression levels of HMGCS2 and SLC22A1 were higher in tumor-adjacent tissues; while the expression levels of G6PD were higher in HCC tissues." (PMID 35392063, 2022). "In the present study, G6PD was strongly correlated with the expression of immune checkpoint molecules, suggesting that G6PD overexpression induces immune escape of tumour cells in HCC." (PMID 35712981, 2022). "In summary, we demonstrated the tumor-suppressing function of circ_0003215 in regulating the PPP via the circ_0003215/miR-663b/DLG4/G6PD axis." (PMID 36127319, 2022). "Functional studies found that LINC00242 enhanced the glycolysis pathway of tumor cells and promoted cell proliferation through increasing the expression of G6PD via reducing the expression of miR-1-3p." (PMID 36185280, 2022). "Analyses of RNA-seq data and clinical data from TCGA have shown that the G6PD levels correlate with tumor grade, tumor recurrence, and poor patient survival in HCC." (PMID 35890276, 2022). "In glioma cells, upon EGFR activation, Fyn is activated causing the phosphorylation of G6PD at Tyr481, leading to enhanced PPP activity, tumour growth and radiation resistance." (PMID 36217026, 2022). "It has been shown that aspirin inhibits tumor cell proliferation by inducing G6PD acetylation and correspondingly reducing the enzymatic activity of G6PD to increases oxidative stress." (PMID 36091812, 2022). "It is known that G6PD overactivation in tumor cells is regulated at the transcriptional or posttranslational level." (PMID 34354953, 2021). "In the present study, we found that G6PD is highly expressed in Huh7 and Bel7402 cells and that the highly active form of G6PD promotes hepatocyte proliferation and tumour formation." (PMID 33630390, 2021). "Treatment with both siRNA of HPV16 E6 and G6PD significantly inhibited the viability, migration, and invasion, as well as greatly increased the apoptosis rate of tumor cells." (PMID 34692493, 2021). "Next, correlation analysis indicated that expression of c-MYC and KRT6A, LSD1, G6PD were positively correlated in NSCLC tumor tissues." (PMID 34235156, 2021). "More importantly, tumour growth is remarkably inhibited after the expression of G6PD K171Q in the TSP50‐expressing cell compared to that in G6PD wild‐type group." (PMID 33630390, 2021). "On the other hand, G6PD is likely to be particularly important in the context of specific tumor types or genetic events such as NRF2 activation." (PMID 34572981, 2021). "O-GlcNAcylation of glucose-6-phosphate dehydrogenase (G6PD) promotes the pentose phosphate pathway that produces antioxidants and ribose sugars for nucletotide synthesis to support tumor growth in hypoxia." (PMID 34868034, 2021). "Collectively, our findings demonstrate that TSP50‐induced cell proliferation and tumour formation are mediated by G6PD K171 acetylation." (PMID 33630390, 2021).